DGLUCY (D-glutamate cyclase)
Description:
D-glutamate cyclase that converts D-glutamate to 5-oxo-D-proline.
Synonyms: C14orf159; FLJ39975
Tractability: No criterion of Open Targets' tractability assessment is met for any kind of drug.
Gene: Protein-coding gene on chromosome 14 (91,060,044 to 91,226,929, forward strand). Ensembl gene ENSG00000133943.
Subcellular location: Mitochondrion matrix
Subcellular location (Human Protein Atlas): Cytosol
Gene Ontology:
Molecular function: protein binding; D-glutamate cyclase activity
Biological process: glutamate metabolic process
Cellular component: cytosol; mitochondrion; mitochondrial matrix; cytoplasm
Genetic constraint (gnomAD): Loss-of-function variants: 57 observed, 58.48 expected, observed/expected ratio (o/e) 0.97, 90% interval 0.79 to 1.22. The upper end of that interval is the gene's LOEUF score, 1.22, which puts it in group 5 of 6, group 1 being the genes least tolerant of losing a copy. Missense variants: 775 observed, 816.95 expected, observed/expected ratio (o/e) 0.95, 90% interval 0.89 to 1.01. Synonymous variants: 325 observed, 327.66 expected, observed/expected ratio (o/e) 0.99, 90% interval 0.9 to 1.09.
Homologues: Orthologues: chimpanzee DGLUCY (99% identical), macaque DGLUCY (95% identical), rat Dglucy (76% identical), mouse Dglucy (75% identical), guinea pig DGLUCY (59% identical), tropical clawed frog dglucy (55% identical), zebrafish dglucy (52% identical).
Diseases named in the same sentence as DGLUCY in open-access papers:
DGLUCY is named in the same sentence as 3 diseases in open-access papers, as found by Europe PMC text mining. Sharing a sentence is not in itself a finding about the gene and the disease. The quoted sentences say what the papers report.
COVID-19 (1 paper, 2023). A disease caused by infection with severe acute respiratory syndrome coronavirus 2. "Likewise, glutaminolysis was used as an alternative pathway, evidenced by upregulation of glutamate oxidation-regulating genes (GLUD1, DGLUCY) in COVID-19(+) CD8+TM." (PMID 37029220, 2023).
heart failure (1 paper, 2017). Inability of the heart to pump blood at an adequate rate to meet tissue metabolic requirements. "We found that D-glutamate cyclase was decreased in the mouse heart failure model." (PMID 28266638, 2017).
DGLUCY also shares sentences with these, for which no sentence is quoted: Obesity (1 paper).